MIR3945HG (MIR3945 host gene)
Gene: Long non-coding RNA gene on chromosome 4 (184,843,296 to 184,855,751, reverse strand). Ensembl gene ENSG00000251230.
Diseases named in the same sentence as MIR3945HG in open-access papers:
MIR3945HG is named in the same sentence as 4 diseases in open-access papers, as found by Europe PMC text mining. Sharing a sentence is not in itself a finding about the gene and the disease. The quoted sentences say what the papers report.
tuberculosis (2 papers, 2016 to 2022). A chronic, recurrent infection caused by the bacterium Mycobacterium tuberculosis. "On the other side, MIR3945HG, which is overexpressed in macrophages upon infection with Mycobacterium tuberculosis, has been proposed as a candidate marker for the diagnosis of tuberculosis." (PMID 35619054, 2022). "ROC analysis showed that AUC of MIR3945HG V1 and MIR3945HG V2 were over 0.9, while that of ENST00000360485 was lower than 0.8, which indicates that MIR3945HG V1 and MIR3945HG V2 may function as more promising candidate biomarkers for tuberculosis diagnosis." (PMID 27966580, 2016).
tumour (1 paper, 2022). "Besides, we found that AC138035.1, C10orf55, AP005899.1, AC008734.1, AL021154.1 and AC130462.2 were upregulated in tumour tissues than those in adjacent normal tissues, whereas MIR3945HG was downregulated." (PMID 35778526, 2022).
MIR3945HG also shares sentences with these, for which no sentence is quoted: infection (1 paper); leishmaniasis (1).